RNU6-1108P (RNA, U6 small nuclear 1108, pseudogene)
Gene: Small nuclear RNA gene on chromosome 15 (44,927,600 to 44,927,703, reverse strand). Ensembl gene ENSG00000252117.
Homologues: Orthologues: chimpanzee U6 (92% identical), mouse Gm23191 (89% identical), macaque U6 (88% identical). Paralogues in human: RNU6-1332P (98% identical), RNU6-41P (91% identical), RNU6-12P (90% identical), RNU6-13P (90% identical), RNU6-32P (90% identical), RNU6-1 (89% identical), RNU6-116P (89% identical), RNU6-15P (89% identical), RNU6-17P (89% identical), RNU6-18P (89% identical), RNU6-2 (89% identical), RNU6-25P (89% identical), and 1292 more.